OR10X1 (olfactory receptor family 10 subfamily X member 1)
Description:
Odorant receptor.
Synonyms: OR10X1P; OR1-13; OR1-14
Tractability: Antibody: its Gene Ontology location is reachable by antibodies, with high confidence; UniProt places it where antibodies can reach, with medium confidence; UniProt predicts a signal peptide or a membrane-spanning region.
Gene: Protein-coding gene on chromosome 1 (158,578,919 to 158,579,899, reverse strand). Ensembl gene ENSG00000279111.
Subcellular location: Cell membrane
Pathways (Reactome):
Sensory Perception: Expression and translocation of olfactory receptors; Olfactory Signaling Pathway
Gene Ontology:
Molecular function: G protein-coupled receptor activity; olfactory receptor activity
Biological process: detection of chemical stimulus involved in sensory perception of smell; G protein-coupled receptor signaling pathway
Cellular component: plasma membrane; membrane
Genetic constraint (gnomAD): Loss-of-function variants: 0 observed, 0.23 expected, observed/expected ratio (o/e) 0, 90% interval 0 to 1.87. That is too few expected variants to judge how well the gene tolerates losing a copy. Missense variants: 449 observed, 407.33 expected, observed/expected ratio (o/e) 1.1, 90% interval 1.02 to 1.19. Synonymous variants: 179 observed, 148.59 expected, observed/expected ratio (o/e) 1.2, 90% interval 1.07 to 1.36.
Homologues: Orthologues: rabbit OR10X1 (82% identical), rat Or10x1b (79% identical), mouse Or10x1 (78% identical), rat Or10x1 (78% identical), guinea pig OR10X1 (77% identical), mouse Or10x4 (74% identical), dog OR10H4D (46% identical). Paralogues in human: OR11G2 (37% identical), OR11H6 (37% identical), OR11H4 (37% identical), OR11H2 (36% identical), OR11H1 (36% identical), OR11H12 (36% identical), OR11H7 (36% identical), OR9G1 (36% identical), OR9A4 (35% identical), OR9A2 (35% identical), OR11A1 (34% identical), OR9A1P (33% identical), and 21 more.